PPM1F (protein phosphatase, Mg2+/Mn2+ dependent 1F)
Description:
Dephosphorylates and concomitantly deactivates CaM-kinase II activated upon autophosphorylation, and CaM-kinases IV and I activated upon phosphorylation by CaM-kinase kinase. Promotes apoptosis.
Synonyms: CaMKPase; hFem-2; KIAA0015; POPX2; FEM-2; CAMKP
Tractability: Antibody: the Human Protein Atlas places it where antibodies can reach. PROTAC: ubiquitination databases record sites on it; its protein half-life has been measured.
Target class: Enzyme; Hydrolase
Gene: Protein-coding gene on chromosome 22 (21,919,425 to 21,952,848, reverse strand). Ensembl gene ENSG00000100034.
Subcellular location (Human Protein Atlas): Nucleoplasm; Plasma membrane
Pathways (Reactome):
Neuronal System: Negative regulation of NMDA receptor-mediated neuronal transmission
Gene Ontology:
Molecular function: calmodulin-dependent protein phosphatase activity; protein binding; protein serine/threonine phosphatase activity; protein tyrosine/serine/threonine phosphatase activity; cation binding; phosphoprotein phosphatase activity
Biological process: cellular response to xenobiotic stimulus; intracellular signal transduction; negative regulation of cell-cell adhesion mediated by cadherin; negative regulation of DNA-templated transcription; negative regulation of protein transport; positive regulation of cell migration; positive regulation of cell-substrate adhesion; positive regulation of chemotaxis; positive regulation of epithelial cell migration; positive regulation of focal adhesion assembly; positive regulation of gene expression; positive regulation of growth; positive regulation of stress fiber assembly; regulation of protein localization
Cellular component: cytosol; protein-containing complex; nucleus; perinuclear region of cytoplasm
Genetic constraint (gnomAD): Loss-of-function variants: 18 observed, 30.89 expected, observed/expected ratio (o/e) 0.58, 90% interval 0.4 to 0.86. The upper end of that interval is the gene's LOEUF score, 0.86, which puts it in group 3 of 6, group 1 being the genes least tolerant of losing a copy. Missense variants: 521 observed, 601.14 expected, observed/expected ratio (o/e) 0.87, 90% interval 0.81 to 0.93. Synonymous variants: 241 observed, 247.46 expected, observed/expected ratio (o/e) 0.97, 90% interval 0.88 to 1.08.
Homologues: Orthologues: chimpanzee PPM1F (99% identical), macaque PPM1F (96% identical), dog PPM1F (82% identical), rabbit PPM1F (82% identical), pig PPM1F (79% identical), mouse Ppm1f (78% identical), rat Ppm1f (78% identical), guinea pig PPM1F (71% identical), tropical clawed frog ppm1f (48% identical), zebrafish ppm1f (47% identical), Drosophila melanogaster CG10376 (28% identical), Drosophila melanogaster alph (20% identical), and 7 more. Paralogues in human: PPM1E (47% identical), ILKAP (24% identical), PPM1N (23% identical), PPM1G (21% identical), PPM1K (21% identical), PP2D1 (20% identical), PPM1J (20% identical), PPM1M (20% identical), PDP2 (20% identical), PPM1H (20% identical), PPM1L (20% identical), PPM1D (20% identical), and 4 more.
Diseases named in the same sentence as PPM1F in open-access papers:
PPM1F is named in the same sentence as 38 diseases in open-access papers, as found by Europe PMC text mining. Sharing a sentence is not in itself a finding about the gene and the disease. The quoted sentences say what the papers report.
breast carcinoma (14 papers, 2015 to 2025). "PPM1F expression was associated with smoking behavior and was higher in the patients with advanced-stage (stages 3-4) breast cancer than in those with early-stage breast cancer." (PMID 27769050, 2016). "PPM1F expression levels were higher in MDA-MB 231 breast carcinoma cells and HepG2 hepatocellular carcinoma cells compared to epithelial-like MCF-7 cells." (PMID 40537771, 2025). "Concordantly, one of its potential targets, PPM1F, has been reported to promote migration and invasion in breast cancer cells." (PMID 32024530, 2020). "Ten paired samples were arbitrarily selected from breast cancer patients (n = 167), and PPM1F protein levels were determined by immunoblotting analysis." (PMID 27769050, 2016). "PPM1F expression was higher in breast cancer cell lines (BT474, MDA-MB-231, MDA-MB-453) than in normal breast cell lines (HBL100 and MCF-10A)." (PMID 27769050, 2016). "The levels of PPM1F protein are higher in invasive MDA-MB-231 breast cancer cells than in noninvasive MCF7 cells." (PMID 27769050, 2016). "Higher levels of PPM1F were detected in the breast cancer tissues of heavy smokers (n=7, 12.8-fold) greater than of non-smokers (n= 28, 6.3-fold) (**p=0.01)." (PMID 27769050, 2016). "MicroRNA-200c, which was previously reported to suppress the epithelial-mesenchymal transition, was recently demonstrated to do so mainly by repressing the migration and invasion of breast cancer cells by downregulating PPM1F." (PMID 27769050, 2016). "In this study, higher levels of PPM1F were detected in breast cancer tissue from heavy smokers (12.8-fold) with advanced-stage disease (stages 3-4) than in non-smokers with advanced-stage disease (6.3-fold)." (PMID 27769050, 2016). "For example, miR-200c targeted PPM1F to suppress invasion, migration, cell polarization, and stress fiber formation in metastatic breast cancer cells by regulating the reorganization of the cytoskeleton." (PMID 26498692, 2015). "PPM1F is reportedly up-regulated in various cancer cell types and involved in breast cancer metastasis." (PMID 26498692, 2015). "PPM1F is reportedly up-regulated in various cancer cell types, including cervical cancer, gastric cancer, breast cancer and neuroblastoma, compared with cell lines that are derived from normal tissues." (PMID 26498692, 2015). "miR-200c can reportedly directly target PPM1F and repress breast cancer cell invasion and migration by modulating the actin cytoskeleton reorganization during EMT." (PMID 26498692, 2015). "All these results suggested that PPM1F could promote smoking-induced breast cancer." (PMID 27769050, 2016). "Studies have shown that PPM1F could affect MLC2 phosphorylation in breast cancer." (PMID 26498692, 2015). "For example, miR-200c and miR-149 inhibit the invasion and metastasis in breast cancer and HCC by targeting PPM1F, but miR-590 has the tumor promoting effects in GC by targeting PPM1F." (PMID 30470261, 2018). "For instance, miR-200 was shown to target cytoskeleton remodeling proteins in breast cancer cells, including WASF3, Moesin, FHOD1, PPM1F, WIPF1 and Cofilin2, functional mediators of miR-200 in the suppression of invasion and/or metastasis." (PMID 26334393, 2015).
breast carcinoma (continued). "PPM1F, expressed in various tumor cell lines, has been shown to dephosphorylate and downregulate PAK activity, with reports indicating its role in modulating breast cancer cell invasion." (PMID 38902322, 2024). "A study on the breast cancer cell line, MB-231, showed that miR-200c mimics reduced expression of formin homology domain-containing protein 1 (FHOD1) and Mg2+/Mn2+-dependent protein phosphatase 1F (PPM1F), in conjunction with reduced invasive capacities of these MB-231 cells." (PMID 27601996, 2016). "Transient transfection of miR-200c reduced both formin homology domain-containing protein 1 (FHOD1) and Mg2+/Mn2+-dependent protein phosphatase 1F (PPM1F) levels, and inhibition of the miR-200b/c/429 cluster in MCF7 breast cancer cells increased FHOD1 and PPM1F levels." (PMID 25762624, 2015). "In addition, PPM1F reportedly increases the phosphorylation of MLC2, which promotes breast cancer metastasis." (PMID 26498692, 2015).
hepatocellular carcinoma (5 papers, 2015 to 2025). A malignant tumor that arises from hepatocytes. "But, the underlying mechanisms by which ncRNAs regulate PPM1F expression in hepatocellular carcinoma (HCC) are poorly understood." (PMID 30470261, 2018). "PPM1F overexpression has been reported in various types of human cancer including hepatocellular carcinoma, breast and colon cancer, where PPM1F expression levels correlated with increased invasiveness and metastatic behaviour." (PMID 40537771, 2025). "CircSLC3A2 functions as an oncogenic factor in hepatocellular carcinoma by sponging miR-490-3p and regulating PPM1F expression." (PMID 32733789, 2020). "In addition, it was shown that miRNA-149 directly targeted CAMKP (also denoted PPM1F) in hepatocellular carcinoma (HCC) and downregulation of this microRNA positively correlated with metastasis development." (PMID 31991573, 2020).
gastric cancer (4 papers, 2015 to 2025). A primary or metastatic malignant neoplasm involving the stomach. "However, our previous study showed that PPM1F is downregulated in gastric cancer (GC), and low expression of PPM1F is associated with poor survival in patients with GC." (PMID 30470261, 2018).
Anxiety (3 papers, 2023 to 2025). Intense feelings of nervousness, tension, or panic often arise in response to interpersonal stresses. "The Ppm1f gene is regulated by stress in mice and is associated with anxiety, depression and PTSD in humans." (PMID 39580604, 2025). "The Ppm1f gene was found to be regulated by stress in mice as well as associated with anxiety and PTSD in humans." (PMID 39580604, 2025). "In addition, an association between dysfunctional levels of PPM1F in the mPFC and depression and anxiety has been revealed in both animals and humans." (PMID 37309288, 2023). "Our previous research found that dysfunctional elevation of PPM1F expression in the hippocampus is a crucial factor affecting depression and anxiety, and bidirectional modulation of PPM1F expression in the dentate gyrus can produce diverse phenotypes associated with depression and anxiety." (PMID 37309288, 2023). "Our previous studies revealed that significant upregulation of PPM1F in the hippocampus is related to the behavioral and pathological states of depression and anxiety." (PMID 37309288, 2023).
breast tumor (3 papers, 2016 to 2022). "PPM1F (also known as POPX2) is a Ser/Thr protein phosphatase that is overexpressed during breast tumor invasion." (PMID 27769050, 2016). "All these results suggested that PPM1F is involved in breast tumor formation." (PMID 27769050, 2016). "Amongst the genes of the proposed miR-200c MΦ migration signature, PPM1F and MSN were already established as miR-200c targets, altering the motility of breast tumor cells." (PMID 35336722, 2022). "In this study, we found higher levels of PPM1F in breast tumor tissues from smokers than from non-smokers." (PMID 27769050, 2016).
depression (2 papers, 2023 to 2025). "To examine the role of PPM1F in depression, we packaged an adeno‐associated virus mediating PPM1F knockdown using a short hairpin RNA (AAV‐shRNA‐GFP) strategy under the CaMKII promoter, which specifically targets excitatory neurons." (PMID 37309288, 2023). "Furthermore, downregulation of PPM1F in the mPFC increased depressive behaviors, validating the causal relationship between PPM1F and depression." (PMID 37309288, 2023). "However, how chronic stress causes a change in PPM1F expression in the mPFC, the neuronal populations and targeted genes of p300 mediating regulation of the effects of PPM1F on depression require further exploration." (PMID 37309288, 2023). "In addition, we tested whether knockdown of PPM1F regulates the neuronal excitability of pyramidal neurons in the mPFC, and identified the causal relationship between neuronal excitability and depression‐related behaviors." (PMID 37309288, 2023). "We then used an adeno‐associated virus strategy to determine the impact of knockdown or overexpression of PPM1F in the excitatory neurons on depression‐related behaviors under basal and stress conditions in both male and female mice." (PMID 37309288, 2023). "The depression‐related behavior induced by PPM1F knockdown after AMPKα2 knockout or the antidepressant activity of PPM1F overexpression after inhibiting acetylation activity of p300 was evaluated." (PMID 37309288, 2023). "Molecularly, PPM1F knockdown decreased the excitability of pyramidal neurons in the mPFC, and restoring this low excitability decreased the depression‐related behaviors induced by PPM1F knockdown." (PMID 37309288, 2023). "We also examined the expression levels of p300 after PPM1F knockdown, accompanied by abnormal AMPK phosphorylation levels, and tested the depression‐related behaviors induced by PPM1F knockdown after AMPKα2 knockout." (PMID 37309288, 2023). "Our findings demonstrate that PPM1F in the mPFC modulates depression‐related behavioral responses by regulating the function of p300 via the AMPK signaling pathway." (PMID 37309288, 2023). "Overall, inhibiting AMPK activity was found to impede the depression‐related phenotypes induced by PPM1F knockdown in the mPFC." (PMID 37309288, 2023). "An adeno‐associated virus strategy was applied to determine the impact of knockdown or overexpression of PPM1F in the excitatory neurons on depression‐related behaviors under basal and stress conditions in both male and female mice." (PMID 37309288, 2023). "Conditional knockout of AMPK revealed an antidepressant phenotype, which can also block depression‐related behaviors induced by PPM1F knockdown." (PMID 37309288, 2023). "Protein phosphatase Mg2+/Mn2+‐dependent 1F (PPM1F) is a serine/threonine phosphatase, and its dysfunction in depression in the hippocampal dentate gyrus has been previously identified." (PMID 37309288, 2023). "shRNA‐mediated genetic knockdown of PPM1F in the mPFC produced depression‐related behaviors, while overexpression of PPM1F alleviated these behavioral responses in CUS‐exposed mice." (PMID 37309288, 2023). "In the present study, we found that the expression of PPM1F was enclosed in the excitatory pyramidal neurons in the mPFC, and the abnormal expression of PPM1F played a pivotal role in the process of depression." (PMID 37309288, 2023). "We aimed to explore whether PPM1F in the mPFC participates in the pathological process of depression." (PMID 37309288, 2023). "Behavioral alterations relevant to depression emerged with short hairpin RNA (shRNA)‐mediated genetic knockdown of PPM1F in the mPFC, while overexpression of PPM1F produced antidepressant activity and ameliorated behavioral responses to stress in CUS‐exposed mice." (PMID 37309288, 2023). "Next, we used a chemogenetic approach to determine whether the activation of blocked neuronal excitability of the neurons in the mPFC induced by PPM1F knockdown was sufficient to reverse depression‐related behaviors." (PMID 37309288, 2023).
depression (continued). "We explored the functional relevance of PPM1F in the pathogenesis of depression." (PMID 37309288, 2023). "Therefore, we raised the hypnosis that depression was developed from the downregulation of PPM1F, which enables the activation of AMPK, leading to the blocking effect of the p300‐associated transcriptional promoter." (PMID 37309288, 2023). "Furthermore, we measured the effects of PPM1F overexpression in the mPFC on depression‐related behaviors under stress conditions by subjecting the mice to CUS." (PMID 37309288, 2023). "To identify whether AMPK is a pivotal and integral mediator in the relationship between PPM1F and depression, we further investigated whether abolishing AMPK activity by knockout of AMPK can contradict depression‐related behaviors in PPM1F knockdown mice." (PMID 37309288, 2023). "However, it remains unclear whether PPM1F in the mPFC is involved in the pathogenesis of major depression." (PMID 37309288, 2023). "The unexpected and notable results in this study were the opposite modulation of PPM1F expression in the mPFC of CUS treated mice compared to the hippocampal expression levels in our previous reports, with the discrepant role in affecting depression‐related behaviors and underlying mechanism." (PMID 37309288, 2023). "In this study, we first established a depression‐related animal model induced by chronic unpredictable stress (CUS) and analyzed the gene expression levels of PPM1F in the mPFC in relation to depressive behaviors." (PMID 37309288, 2023). "Chronic unpredictable stress decreased the expression levels of PPM1F in the mPFC, which activated the AMPK signaling pathway, downregulated the expression levels and acetylase activity of p300, and resulted in the formation of depression." (PMID 37309288, 2023). "However, an unexpected finding was that the infusion of C646, which is a small‐molecule specific inhibitor of p300, to the mPFC, could not induce depression‐related behaviors in either the basal or subthreshold CUS conditions, but partially blocked the antidepressive effect of PPM1F overexpression." (PMID 37309288, 2023).
neuroblastoma (2 papers, 2015 to 2025). Neuroblastoma (NB) is the most common solid, extracranial childhood tumor. "To verify the severe migration defect of neuroblastoma cells upon lack of PPM1F, we created a second, independent PPM1F-deficient cell line by CRISPR/Cas9-mediated disruption of the PPM1F gene in the SH-SY5Y neuroblastoma cell line." (PMID 40537771, 2025).
Alzheimer disease (1 paper, 2022). A progressive, neurodegenerative disease characterized by loss of function and death of nerve cells in several areas of the brain leading to loss of cognitive function such as memory and language. "The Tau/MAPT was also enriched in the “Tau pathology in Alzheimer disease” pathway together with protein phosphatase; PPM1F was identified in the pathway as the PP2C group with the highest expression in the SOY1.5 group." (PMID 35804531, 2022).
biliary cirrhosis (1 paper, 2021). "Other high GGT putative cholangio-ciliopathies caused by mutations in Kinesin family member 12 (KIF12), and protein phosphatase 1F (PPM1F) also have histopathologic features suggestive of biliary cirrhosis ± paucity of bile ducts and liver fibrosis." (PMID 33853651, 2021).
bipolar disorder (1 paper, 2013). A disorder of the brain that causes unusual shifts in mood, energy, activity levels and the ability to carry out day-to-day tasks. "Very recently, genome-wide association studies suggested that single nucleotide polymorphisms found in the loci for CaMKP-N (PPM1E) and for CaMKP (PPM1F) are associated with testicular germ cell tumor and with both schizophrenia and bipolar disorders, respectively." (PMID 23991411, 2013).
endometrial cancer (1 paper, 2024). Primary or metastatic malignant neoplasm involving the endometrium (mucous membrane that lines the endometrial cavity). "Our immunohistochemical study showed that the expression of BHLHE40, PPM1F, and phosphorylated AMPKα correlated with the prognosis of endometrial cancer patients." (PMID 38301894, 2024).
familial intrahepatic cholestasis (1 paper, 2022). An instance of intrahepatic cholestasis that is caused by an inherited modification of the individual's genome. "Furthermore, PPM1F has been implicated to play a role in familial intrahepatic cholestasis, where one affected, consanguineous, family was identified." (PMID 36313552, 2022). "Furthermore, PPM1F is a variant of unknown significance in familial intrahepatic cholestasis, and PPM1K has a homozygous association with maple syrup urine disease." (PMID 36313552, 2022).